IRF5 (interferon regulatory factor 5)
Diseases named in the same sentence as IRF5 in open-access papers (continued):
Sharing a sentence is not in itself a finding about the gene and the disease.
Sepsis (3 papers, 2017 to 2023). Sepsis is defined as life-threatening organ dysfunction caused by a dysregulated host response to infection. "Thus, in the re-polarization model, knockdown of IRF5 induces both anti-inflammatory tissue regeneration and immune effects to reduce infection burden and inhibit sepsis." (PMID 29773788, 2018). "Upon the work and the consensus between the IRF5 binding site and MS19, it was hypothesized that MS19 could prevent the IRF5 from binding the regulatory elements of the pro-inflammatory gene and therefore inhibit the development of sepsis." (PMID 28492513, 2017). "Possibly, MS19 could be used as therapeutic oligonucleotides for the treatment of sepsis in humans by inhibiting IRF5 in the dysfunctional macrophages." (PMID 28492513, 2017). "Overall, the data provided here not only demonstrates the inhibitory roles of MS19 on macrophages involved inflammatory response in the development of sepsis, but also reveals a novel mechanism of MS19 mediated inhibition on IRF5 nuclear translocation in macrophages." (PMID 28492513, 2017).
Type 1 Diabetes (3 papers, 2007 to 2019). "As genes associated with immune-mediated diseases have an increased prior probability of being associated with other immune-mediated diseases, we tested three such genes, IL23R, IRF5 and CD40, for an association with type 1 diabetes." (PMID 18045485, 2007). "Lack of association of IL23R, IRF5 and CD40 with type 1 diabetes helps to delineate pathogenic mechanisms between type 1 diabetes and other immune-mediated diseases, especially when the associations reported for the other diseases are highly likely to be true positive results." (PMID 18045485, 2007).
adult T-cell leukemia (2 papers, 2009 to 2011). "More recently, a single point mutation in the IRF5 gene was identified in peripheral blood from patients with adult T-cell leukemia/lymphoma (ATL) and chronic lymphocytic leukemia (CLL) that altered the function of wild-type IRF5." (PMID 22053985, 2011).
atypical ductal hyperplasia (2 papers, 2011 to 2024). Atypical ductal hyperplasia is an atypical proliferative lesion that falls in between the continuum from normal hyperplasia to low grade ductal carcinoma in situ. "Previously, we reported that normal breast tissue and tissue revealing atypical ductal hyperplasia (ADH) stained positive for IRF5 expression, whereas only ~ 38% of DCIS and ~ 10% of IDC retained IRF5 expression." (PMID 38969706, 2024). "Formalin-fixed paraffin-embedded archival breast tissue specimens from patients with atypical ductal hyperplasia (ADH), ductal carcinoma in situ (DCIS) and invasive ductal carcinoma (IDC) were examined for their expression of IRF1 and IRF5." (PMID 22053985, 2011).
B-cell lymphoma (2 papers, 2012 to 2023). "7q32 deletions cover IRF5, a known tumor suppressor in B-cell lymphoma, while individuals with NF1 loss are at increased risk for NHL." (PMID 37495858, 2023). "The deletion polymorphism in IRF5 exon 6 (rs60344245) found in SMZL was also seen at comparable frequencies in other B-cell lymphomas and a normal control population from Germany." (PMID 23028731, 2012).
cervical cancer (2 papers, 2024 to 2025). A primary or metastatic malignant neoplasm involving the cervix. "The METTL3-induced transcription factor interferon regulatory Factor 5 (IRF5) promotes proliferation, migration, invasion, and angiogenesis in cervical cancer (CC) cells by upregulating the protein phosphatase 6 catalytic subunit (PPP6C)." (PMID 39295872, 2024).
Chlamydia infection (2 papers, 2017 to 2019). "IRF5 iPSdM knockouts were more susceptible to Chlamydia infection, highlighting a role for IRF5 in limiting Chlamydia infection." (PMID 30199605, 2019). "Due to the apparent importance of the Type I interferon response, we targeted the interferon regulatory factor (IRF) family transcription factor IRF5 that was 3.4-fold upregulated by Chlamydia infection." (PMID 28440293, 2017).
Coronary Artery Disease (2 papers, 2021 to 2022). "Interferon regulatory factor 5 (IRF5) has an important role in the inflammatory process, a fundamental component of coronary artery disease (CAD)." (PMID 33802675, 2021).
ductal carcinoma in situ (2 papers, 2011 to 2015). "Our lab previously showed that normal breast epithelium expresses high levels of IRF5 and that this expression decreases as malignancy progresses from ductal carcinoma in situ (DCIS) to invasive ductal carcinoma (IDC)." (PMID 25649192, 2015). "We previously found that expression of the transcription factor interferon regulatory factor 5 (IRF5) is significantly decreased as a breast lesion progresses from a non-malignant stage to ductal carcinoma in situ and is eventually lost in ~80% of invasive ductal carcinomas examined." (PMID 25649192, 2015).
endothelial dysfunction (2 papers, 2016 to 2025). In vascular diseases, endothelial dysfunction is a systemic pathological state of the endothelium (the inner lining of blood vessels) and can be broadly defined as an imbalance between vasodilating and vasoconstricting substances produced by (or acting on) the endothelium. "Accordingly, we developed a decoy peptide inhibitor of IRF5 to investigate the role of IRF5 in myocardial and endothelial dysfunction in Tsk/+ mice." (PMID 27050551, 2016). "However, little is known regarding the physiological function of IRF5 in endothelial dysfunction in salt-sensitive hypertension." (PMID 40332339, 2025). "In contrast, the present study elucidates the IRF5-STAT axis as an upstream transcriptional regulator of ESM1 from the endothelial perspective, expanding the regulatory network and providing a theoretical basis for potential SSH therapeutic strategies targeting endothelial dysfunction." (PMID 40332339, 2025).
esophageal cancer (2 papers, 2024 to 2025). A primary or metastatic malignant neoplasm involving the esophagus. "In addition, overexpression of IRF2 promotes esophageal cancer cell proliferation and mutations of SNPs in genes such as IRF3, IRF5, and IRF7 may facilitate the progress of esophageal cancers, while IRF4 may be regarded as a protective factor in ESCC." (PMID 39384770, 2024).
experimental autoimmune encephalomyelitis (2 papers, 2025). An autoimmune demyelinating disease of the central nervous system that is produced experimentally in animals by the injection of homogenized brain or spinal cord in Freund's adjuvant. "Irf5-/- mice exhibited increased damage in an experimental autoimmune encephalomyelitis (EAE) model and demonstrated impaired oligodendrocyte recruitment into the lesion core following lysolecithin-induced demyelination." (PMID 40137979, 2025).
glomerulonephritis (2 papers, 2017 to 2024). A renal disorder characterized by damage in the glomeruli. "In IRF5−/− MRL/lpr mice, IFNα and autoantibody production were markedly reduced, and glomerulonephritis was much improved." (PMID 29333443, 2017).
Granuloma (2 papers, 2011 to 2012). A compact, organized collection of mature mononuclear phagocytes, which may be but is not necessarily accompanied by accessory features such as necrosis. "Granulomas in Irf5-/- mice are characterized by an increased IL-4 and IL-10 response and concomitant low iNOS expression." (PMID 21253574, 2011). "Additionally, the granulomas in Irf5−/− mice were also considerably smaller in size suggesting a defective recruitment of inflammatory cells into the liver of Irf5−/− mice." (PMID 21811511, 2012). "Since Irf5-/- granulomas were not the typical Th1-type granulomas which develop in infected WT mice and, unlike WT mice, Irf5-/- mice failed to eliminate the parasites, we next examined the cytokine environment in the livers of both groups of mice." (PMID 21253574, 2011).
Hypoglycemia (2 papers, 2020 to 2021). A decreased concentration of glucose in the blood. "Interestingly, we found that hypoglycemia, whether persistent or repetitive-intermittent, induced the expression of IRF5, nearly 2-fold, in THP-1 macrophages as compared to the normoglycemic control." (PMID 32806763, 2020).
hypothyroidism (2 papers, 2019 to 2023). Abnormally low levels of thyroid hormone. "Our study identified IRF5 as a potential risk gene for hypothyroidism and RA, but further validation with larger sample sizes and functional experiments is needed." (PMID 38332917, 2023). "A comprehensive approach integrating PLACO, Bayesian colocalization analysis, MTAG, and TWAS, we successfully identified TYK2, IL2RA, and IRF5 as shared risk genes for both hypothyroidism and RA." (PMID 38332917, 2023). "Among these, 12 genes, including TYK2 and IRF5, were implicated in RA (discovery), RA (replication), and hypothyroidism, according to TWAS." (PMID 38332917, 2023). "This comprehensive approach identified TYK2, IL2RA, and IRF5 in hypothyroidism and RA (discovery) utilizing four or three methods." (PMID 38332917, 2023). "TYK2 was consistently identified by all four methods used, while IL2RA and IRF5 were identified in the hypothyroidism and RA (replication) studies using two or three of these methods." (PMID 38332917, 2023).
interstitial lung disease (2 papers, 2020 to 2023). A diverse group of lung diseases that affect the lung parenchyma. "IRF5 SNP rs2004640 and rs2280714 are identified as a risk factor for SSc in whites and Asians., however rs4728142 is associated with lower IRF5 gene expression, longer survival and milder interstitial lung disease of SSc patients." (PMID 37638030, 2023).
leprosy (2 papers, 2015 to 2022). Leprosy is a chronic infectious disease affecting primarily the skin and peripheral nervous system. "Thereby the suppression of IRF5 and IL-12/23 secretion by PAR1 gene, can provides a novel mechanism by which the host suppresses the Th1 and Th17response to infection, and dysregulation of this process can likely an important factor in the susceptibility of some individuals to leprosy." (PMID 26367014, 2015).
leukemia (2 papers, 2021 to 2022). A malignant (clonal) hematologic disorder, involving hematopoietic stem cells and characterized by the presence of primitive or atypical myeloid or lymphoid cells in the bone marrow and the blood. "Upregulation of IRF5 network potentially indicates an increase of inflammation in leukemia patients, although inflammation alone is inefficient to clean up leukemia cells." (PMID 33408321, 2021). "Compared to healthy BMMCs, we observed the TF networks of ZNF266, RORA, GTF3C2, ZNF76, ZNF383, IRF5 and NFE2L2 being top upregulated in all leukemia patients." (PMID 33408321, 2021). "Moreover, p21 was unlikely to be involved in the proinflammatory reprogramming of MDMs following leukemia cell engulfment, since p21 overexpression and p21 knockdown failed to modulate the expression of CD163 and IRF5, respectively." (PMID 36347876, 2022).
liver cancer (2 papers, 2022 to 2023). An epithelial or non-epithelial malignant neoplasm that arises from the liver. "Subsequently, IRF5 protein expression is suppressed, inhibiting the proliferation of HepG2 liver cancer cells." (PMID 38192621, 2023). "Therefore, IRF5 may be a potential target for the treatment of liver cancer." (PMID 38192621, 2023). "The expression of FCN2 was negatively correlated with the M1 macrophage biomarker (IRF5), neutrophil biomarker (ITGAM), and DC biomarker (ITGAX) in liver cancer." (PMID 36425563, 2022).
myocardial inflammation (2 papers, 2016 to 2024). "The goal of this study was to design and develop a decoy peptide to inhibit IRF5 and determine its effects on myocardial inflammation and vascular EC function in Tsk/+ mice, a murine model of myocardial inflammation and fibrosis and impaired vasodilatation." (PMID 27050551, 2016). "Here we report on the development of a novel decoy peptide inhibitor of IRF5 that decreases myocardial inflammation and improves vascular endothelial cell (EC) function in tight-skin (Tsk/+) mice." (PMID 27050551, 2016).
neuropathic pain (2 papers, 2019 to 2022). Chronic pain caused by damage to nerve fibers. "Among the families of purinergic ionotropic receptors and Interferon Regulatory Factors, both IRF5 and P2X4R have been indicated in microglia activation and the development of neuropathic pain via an IRF5/P2X4R axis." (PMID 35806200, 2022).
peripheral nerve injury (2 papers, 2018 to 2020). Injury to a peripheral nerve. "IRF5 has also been shown to be responsible for microglia mediated neuropathic pain after peripheral nerve injury (PNI), the expression of which was up-regulated in microglia after PNI." (PMID 33362784, 2020).
pneumonia (2 papers, 2014 to 2017). An acute, acute and chronic, or chronic inflammation focally or diffusely affecting the lung parenchyma, caused by an infection in one or both of the lungs (by bacteria, viruses, fungi, or mycoplasma.). "In an independent set of samples assayed using RT-qPCR, Ifnar2 and the interferon-responsive genes Cxcl11, Ifit1, Irf5 and Isg15 were confirmed to be upregulated during pneumonia." (PMID 28900269, 2017). "Interestingly, in the interferon signaling pathways, Ifnar2 and the interferon-responsive genes Cxcl11, Ifit1, Irf5 and Isg15 were verified to be upregulated during pneumonia, documenting that neutrophils are well able to respond to type I interferon signaling." (PMID 28900269, 2017).
pulmonary fibrosis (2 papers, 2021 to 2022). Chronic progressive interstitial lung disorder characterized by the replacement of the lung tissue by connective tissue, leading to progressive dyspnea, respiratory failure, or right heart failure. "Deletion of CB1R also attenuated bleomycin-induced increase in IRF5 in lungs and protected from pulmonary fibrosis." (PMID 34650521, 2021).
Thrombocytosis (2 papers, 2023). Increased numbers of platelets in the peripheral blood. "Another result is that irf5 increases after let-7b and mir-223 knockdowns but a reduction in irf5 shows a group of larvae with shortened TTO that is consistent with thrombocytosis, and this is contradicting." (PMID 37752184, 2023). "Another result is that irf5 increases after let-7b and mir-223 knockdowns but a reduction in irf5 results shows a group of larvae with shortened TTO that is consistent with thrombocytosis, and this is contradicting." (PMID 37162944, 2023).
thyroid cancer (2 papers, 2012 to 2017). "To investigate the molecular mechanism underlying the unexpected effects of IRF5, we evaluated B-Raf expression, as this protein is mutated in 30-40% of thyroid carcinomas." (PMID 22507190, 2012). "To establish the tumor-promoting effect of endogenous IRF5 on thyroid cancer cells, we silenced its expression using the doxycicline inducible pTRIPZ vector (shRNA anti-IRF5, gene ID NM_001098627, Open Biosystems)." (PMID 22507190, 2012). "To assess IRF5 intracellular distribution, we isolated nuclear and cytoplasmic fractions from four thyroid cancer cells using the Qproteom Nuclear Protein Kit (Qiagen)." (PMID 22507190, 2012). "On the contrary, IRF5 stimulated thyroid cancer proliferation, protected malignant thyroid cells from the cytotoxic effects of different antiblastic compounds, and significantly increased their colony-forming ability." (PMID 22507190, 2012). "We found both endogenous and ectopic IRF5 in the cytoplasm of thyroid cancer cells and IFNα was unable to relocate the protein in the nucleus." (PMID 22507190, 2012). "Infected thyroid cancer cells were treated with doxycicline (1 μg/mL) for 72 hours, lysed and blotted for IRF5 to confirm reduced expression of the transcription factor." (PMID 22507190, 2012). "Reduced IRF5 expression decreased thyroid cancer colony formation implying that, in thyroid cancer cells, IRF5 facilitates single cell growth." (PMID 22507190, 2012). "On the contrary, primary and immortalized thyroid cancer cells expressed high levels of IRF5, suggesting a possible role for this protein in thyroid carcinogenesis." (PMID 22507190, 2012). "SW1736 were the only thyroid cancer line that displayed a robust up-regulation in IRF5 expression after IFNα." (PMID 22507190, 2012). "We investigated the expression, localization and function of IRF5 in thyroid cancer cells and found that it is highly expressed in both primary and immortalized thyroid carcinomas but not in normal thyrocytes." (PMID 22507190, 2012). "To explore IRF5 function in thyroid cancer cells, we employed lentiviral vectors to over-express this protein in SW1736, WRO, 8305C and C643." (PMID 22507190, 2012). "Our finding that thyroid cancer cells localize IRF5 to the cell cytoplasm implies that the protein is transcriptionally inactive." (PMID 22507190, 2012). "IRF5 over-expression induced a significant increase in the total number of foci generated by three of four cell lines, suggesting that this protein improves the colony-forming ability of individual thyroid cancer cells." (PMID 22507190, 2012). "An IRF5-dependent induction of endogenous B-Raf observed in all thyroid cancer cells might contribute to these unexpected effects." (PMID 22507190, 2012). "Indeed, silencing of endogenous IRF5 by lentiviral shRNA reduces the clonogenic potential of most thyroid cancer cells." (PMID 22507190, 2012). "We have analyzed the expression and function of IRF5 in thyroid carcinoma cells and report here multiple evidence suggesting that IRF5 may contribute to thyroid cancer proliferation and survival." (PMID 22507190, 2012). "Interestingly, ectopic IRF5 induced endogenous B-Raf levels in all thyroid cancer cells." (PMID 22507190, 2012). "However, its efficacy on IRF5 induction in thyroid cancer cells is still unknown." (PMID 22507190, 2012). "We found that IRF5 over-expression conferred a proliferative advantage to three of four thyroid cell lines (SW1736, WRO, and C643) suggesting a role for IRF5 in promoting thyroid cancer growth." (PMID 22507190, 2012). "In this study, we report - for the first time - that IRF5 is expressed in different thyroid carcinoma histotypes and in multiple thyroid cancer cell lines but is not detectable in normal human thyrocytes." (PMID 22507190, 2012).
thyroid cancer (continued). "In primary normal and tumor thyroid cancer cells IFNα does not modulate IRF5 levels while in immortalized cell lines, IRF5 seems oddly responsive to IFNα, since exposure to this cytokine reduces IRF5 in two thyroid cancer cells and consistently increases its expression in one cell line." (PMID 22507190, 2012).
viral myocarditis (2 papers, 2024). Myocarditis that is caused by an infection with a viral agent. "The TLR9 signaling pathway has been reported to promote cardiac inflammation by activating interferon regulatory factor 5 (IRF5) in coxsackievirus B3 (CVB3)-induced viral myocarditis (VMC)." (PMID 38684719, 2024). "Whereas most IFNs and IFN-related pathways have shown to have protective roles in viral myocarditis, IRF5 may play a role in the pathogenesis of cardiac injury in this setting." (PMID 38665231, 2024).
abscesses (1 paper, 2024). "It is suspected that decreased Irf5 leads to decreased macrophage over-activation and enhances the ability of the immune system to clear infections and abscesses." (PMID 39460273, 2024). "This allowed mice treated with Irf5 siRNA to clear abscesses in a musculoskeletal infection challenge." (PMID 39460273, 2024).
alveolitis (1 paper, 2015). "IRF5 rs2004640*TT was found to have a strong association with dcSSc, fibrosing alveolitis, antinuclear antibody (ANA), and ATA positivity in a French cohort." (PMID 26106387, 2015). "Variant rs7574865*T allele has an additive effect with IRF5 rs2004640 seen in fibrosing alveolitis." (PMID 26106387, 2015).
anaplastic astrocytoma (1 paper, 2021). "The results of Sun’s study suggested that IRF5 was increased 2.125-fold in diffuse astrocytoma (p = 1.33E-4) and 2.180-fold in anaplastic astrocytoma (p = 3.20E-5)." (PMID 33902005, 2021).